EXOSC10 (exosome component 10)
Description:
Catalytic component of the RNA exosome complex which has 3'->5' exoribonuclease activity and participates in a multitude of cellular RNA processing and degradation events. In the nucleus, the RNA exosome complex is involved in proper maturation of stable RNA species such as rRNA, snRNA and snoRNA, in the elimination of RNA processing by-products and non-coding 'pervasive' transcripts, such as antisense RNA species and promoter-upstream transcripts (PROMPTs), and of mRNAs with processing defects, thereby limiting or excluding their export to the cytoplasm. Part of the small subunit (SSU) processome, first precursor of the small eukaryotic ribosomal subunit. During the assembly of the SSU processome in the nucleolus, many ribosome biogenesis factors, an RNA chaperone and ribosomal proteins associate with the nascent pre-rRNA and work in concert to generate RNA folding, modifications, rearrangements and cleavage as well as targeted degradation of pre-ribosomal RNA by the RNA exosome. The RNA exosome may be involved in Ig class switch recombination (CSR) and/or Ig variable region somatic hypermutation (SHM) by targeting AICDA deamination activity to transcribed dsDNA substrates. In the cytoplasm, the RNA exosome complex is involved in general mRNA turnover and specifically degrades inherently unstable mRNAs containing AU-rich elements (AREs) within their 3' untranslated regions, and in RNA surveillance pathways, preventing translation of aberrant mRNAs. It seems to be involved in degradation of histone mRNA. EXOSC10 is required for nucleolar localization of C1D and probably mediates the association of MTREX, C1D and MPHOSPH6 with the RNA exosome involved in the maturation of 5.8S rRNA. Plays a role in the recruitment of replication protein A complex (RPA) and RAD51 to DNA double-strand breaks caused by irradiation, contributing to DNA repair by homologous recombination. Regulates levels of damage-induced RNAs in order to prevent DNA-RNA hybrid formation at DNA double-strand breaks and limit DNA end resection after damage. Plays a role in oocyte development, maturation and survival (By similarity). Required for normal testis development and mitotic division of spermatogonia (By similarity). Plays a role in proper embryo development (By similarity). Required for global protein translation. Required for cell proliferation. Regulates metabolism of C9orf72-derived repeat RNA that can be translated into toxic dipeptide repeat proteins.
Synonyms: PM/Scl-100; PMSCL; PMSCL2; RRP6; PM-Scl; Rrp6p; p2; p3; p4
Tractability: Small molecule: a structure with a bound ligand is known; it has a high-quality binding pocket. PROTAC: UniProt records ubiquitination sites on it; ubiquitination databases record sites on it; its protein half-life has been measured.
Target class: Enzyme; Hydrolase
Gene: Protein-coding gene on chromosome 1 (11,066,613 to 11,099,898, reverse strand). Ensembl gene ENSG00000171824.
Subcellular location: Cytoplasm; Nucleus; Nucleus, nucleolus; Nucleus, nucleoplasm
Subcellular location (Human Protein Atlas): Nucleoli; Nucleoli rim; Cytosol; Nucleoplasm
Pathways (Reactome):
Metabolism of RNA: Major pathway of rRNA processing in the nucleolus and cytosol; Nuclear RNA decay
Gene Ontology:
Molecular function: 3'-5'-RNA exonuclease activity; protein binding; RNA binding; RNA exonuclease activity; telomerase RNA binding; 3'-5' exonuclease activity; nucleic acid binding; nucleotide binding
Biological process: CUT catabolic process; histone mRNA catabolic process; maturation of 5.8S rRNA; negative regulation of telomere maintenance via telomerase; nuclear mRNA surveillance; nuclear polyadenylation-dependent rRNA catabolic process; nuclear-transcribed mRNA catabolic process; regulation of telomerase RNA localization to Cajal body; ribosomal small subunit biogenesis; RNA catabolic process; RNA processing; exonucleolytic trimming to generate mature 3'-end of 5.8S rRNA from tricistronic rRNA transcript (SSU-rRNA, 5.8S rRNA, LSU-rRNA); nuclear polyadenylation-dependent antisense transcript catabolic process; nuclear polyadenylation-dependent CUT catabolic process; nuclear polyadenylation-dependent snoRNA catabolic process; nuclear polyadenylation-dependent snRNA catabolic process; poly(A)-dependent snoRNA 3'-end processing; rRNA processing; TRAMP-dependent tRNA surveillance pathway; regulation of gene expression
Cellular component: cytoplasm; cytosol; euchromatin; exosome (RNase complex); membrane; nuclear exosome (RNase complex); nucleolus; nucleoplasm; nucleus; small-subunit processome; cytoplasmic exosome (RNase complex); nucleolar exosome (RNase complex)
Genetic constraint (gnomAD): Loss-of-function variants: 84 observed, 118.18 expected, observed/expected ratio (o/e) 0.71, 90% interval 0.6 to 0.85. The upper end of that interval is the gene's LOEUF score, 0.85, which puts it in group 3 of 6, group 1 being the genes least tolerant of losing a copy. Missense variants: 999 observed, 1,102.3 expected, observed/expected ratio (o/e) 0.91, 90% interval 0.86 to 0.95. Synonymous variants: 387 observed, 407.35 expected, observed/expected ratio (o/e) 0.95, 90% interval 0.87 to 1.03.
Homologues: Orthologues: chimpanzee EXOSC10 (95% identical), macaque EXOSC10 (93% identical), dog EXOSC10 (90% identical), rabbit EXOSC10 (89% identical), guinea pig EXOSC10 (88% identical), mouse Exosc10 (87% identical), rat Exosc10 (87% identical), pig EXOSC10 (86% identical), tropical clawed frog exosc10 (65% identical), zebrafish exosc10 (59% identical), Drosophila melanogaster Rrp6 (34% identical), Caenorhabditis elegans crn-3 (28% identical). Paralogues in human: EXD1 (10% identical).
Diseases named in the same sentence as EXOSC10 in open-access papers:
EXOSC10 is named in the same sentence as 35 diseases in open-access papers, as found by Europe PMC text mining. Sharing a sentence is not in itself a finding about the gene and the disease. The quoted sentences say what the papers report.
polymyositis (6 papers, 2017 to 2025). A rare idiopathic inflammatory myopathy characterized by symmetric proximal muscle weakness and elevated muscle enzymes. "EXOSC10 is the target of auto-antibodies produced in patients suffering from polymyositis/scleroderma overlap syndrome and has broad clinical importance." (PMID 40221814, 2025).
ovarian insufficiency (2 papers, 2023 to 2025). "Our results unambiguously demonstrate an essential role for EXOSC10 in oogenesis and may serve as a model for primary ovarian insufficiency in humans." (PMID 36923944, 2023). "Our work establishes an essential role for Exosc10 in oocyte growth and maturation and may serve as a model for primary ovarian insufficiency in humans." (PMID 36923944, 2023).
breast carcinoma (1 paper, 2024). "Specifically, OXSR1 has been previously reported to mediate the TGF-β signaling pathway in breast cancer, promoting epithelial-mesenchymal transition (EMT) and metastasis through the phosphorylation of Smad2/3, EXOSC10 is a novel candidate factor that had not been identified before." (PMID 39619656, 2024).
cognitive decline (1 paper, 2026). "Remarkably, Exosc10 depletion prevents cognitive decline and restores memory in two different mouse models of β-amyloid neurotoxicity." (PMID 41850724, 2026).
female subfertility (1 paper, 2025). "Conditional deletion of Exosc10 in oocytes from the primordial follicle stage onward, using Gdf9-Cre mice, results in complete female infertility because of impaired oogenesis, defective oocyte maturation, and depletion of the ovarian reserve." (PMID 40513949, 2025). "Oocyte-specific KO of Exosc10 results in female subfertility by impairing germinal vesicle breakdown and disrupting the transcriptome during oocyte maturation." (PMID 40513949, 2025).
Infertility (1 paper, 2023). "The Exosc10cKO(Gdf9) mouse model shows greater penetrance of the phenotype since it causes severe infertility, which could be explained by earlier inactivation of Exosc10 by the Cre recombinase during oogenesis." (PMID 36923944, 2023).
liver cancer (1 paper, 2023). An epithelial or non-epithelial malignant neoplasm that arises from the liver. "Although, recent evidence showed that human EXOSC10 is an unfavorable prognostic marker for liver cancer." (PMID 37701829, 2023). "The expression of EXOSC10 was verified by tissue samples from clinical patients and in vitro experiment (liver cancer cell lines HepG2, MHCC97H and Huh-7; normal human liver cell line LO2)." (PMID 37701829, 2023). "To explore the function of EXOSC10 in liver cancer cells, we chose the Huh-7 liver cancer cell line to study." (PMID 37701829, 2023). "Furthermore, we measured the expression of EXOSC10 mRNA and protein in three liver cancer cell lines (HepG2, MHCC97H and Huh-7) and the normal liver cell line LO2 by quantitative real-time PCR and Western blotting, respectively." (PMID 37701829, 2023). "In vitro, we found that EXOSC10 mRNA and protein were significantly overexpressed in the three liver cancer cell lines (HepG2, MHCC97H, and Huh-7) and the knockdown of EXOSC10 inhibited the proliferation and migration of HCC cells." (PMID 37701829, 2023).
male infertility (1 paper, 2025). The inability of the male to effect fertilization of an ovum after a specified period of unprotected intercourse. "Collectively, these results establish that EXOSC10 is essential for spermatogenesis, with its deletion leading to substantial germ cell loss, defective spermatogenesis, and male infertility." (PMID 40513949, 2025).
ovarian carcinoma (1 paper, 2023). A malignant neoplasm originating from the surface ovarian epithelium. "EXOSC10 is reported to be a tumor-specific antigen in ovarian cancer." (PMID 37701829, 2023).
pancreatic cancer (1 paper, 2022). "We found that knockdown of EXOSC10, but not EXOSC3 or EXOSC9, caused growth inhibition of pancreatic cancer cells." (PMID 35008922, 2022). "EXOSC4 may degrade SESN2 mRNA levels by regulating EXOSC10 and DIS3 family protein levels in pancreatic cancer cells." (PMID 35008922, 2022).
primary ovarian insufficiency (1 paper, 2025). "The latest research suggests that EXOSC10 is essential for the maturation of oocytes, and blocking EXOSC10 activity can cause the rapid depletion of oocytes, disrupting ovarian reserve function and leading to a condition similar to primary ovarian insufficiency (POI)." (PMID 39996063, 2025).
viral infection (1 paper, 2021). "Differentially expressed genes in the viral infection category (174 genes) indicated that keratinocytes had down-regulated genes involved in host gene transcription (DDX56, SMARCA2) and RNA transportation and processing (NUP98, RAE1, XAB2, RBM17, EXOSC10)." (PMID 34552595, 2021).
cancer (5 papers, 2016 to 2026). A tumor composed of atypical neoplastic, often pleomorphic cells that invade other tissues. "In vivo assay, E2F1 deficiency suppressed HCC tumor growth and eliminated cancer stemness, while these effects were abolished by EXOSC10 up-regulation." (PMID 40221814, 2025). "EXOSC10 is a cancer biomarker; its activity is inhibited by the widely used anticancer drug 5-fluorouracil (5-FU) and the protein's depletion sensitizes cells to 5-FU." (PMID 42138069, 2026). "The tumor sphere formation assay showed that EXOSC10 deletion declined the sphere formation rate in Huh-7 and Hep3B cells, as well as impaired the expression of OCT4 and CD44 proteins, indicating the inhibition of cancer cell stemness after EXOSC10 knockdown." (PMID 40221814, 2025). "Genes encoding exosome complex components are linked to pathologies including cancer (DIS3), immune disorders (EXOSC9 and EXOSC10) and congenital neurological disorders (EXOSC3 and EXOSC8)." (PMID 27543448, 2016). "Functionally, we found EXOSC10 overexpression reversed E2F1 deficiency-induced proliferation inhibition, apoptosis enhancement, angiogenesis suppression, and cancer stemness impairment in Huh-7 and Hep3B cells." (PMID 40221814, 2025). "In conclusion, this study first confirmed that E2F1 up-regulated EXOSC10 expression by promoting its transcription, thereby enhancing HCC growth and cancer stemness." (PMID 40221814, 2025). "E2F1 promotes EXOSC10 transcription and then facilitates HCC growth and cancer stemness, revealing a potential target for HCC therapy." (PMID 40221814, 2025). "Here, this study focused on probing the functions of E2F1 and EXOSC10 on HCC growth and cancer stemness, moreover, their interaction in HCC progression were further investigated, which may provide a novel insight into the therapy of HCC." (PMID 40221814, 2025).
tumor (3 papers, 2023 to 2025). "Next, we performed a correlation analysis between EXOSC10 and the tumor microenvironment, immune/stromal/estimate scores in HCC." (PMID 37701829, 2023). "However, the potential correlation of EXOSC10 expression and tumor immune infiltration needs to be further tested experimentally." (PMID 37701829, 2023). "We also found that the expression of the EXOSC10 protein was up-regulated in HCC tissue compared to normal liver tissue by analyzing 20 pairs of HCC samples and adjacent non-tumor tissues." (PMID 37701829, 2023).
EXOSC10 also shares sentences with these, for which no sentence is quoted: myositis (17 papers); systemic sclerosis (7); overlap syndromes (6); scleroderma (4); calcinosis (3); hepatocellular carcinoma (2); immune disorders (2); infection (2); Sclerodermatomyositis (2); autoimmune disease (1); colon cancer (1); COVID-19 (1); dilated cardiomyopathy (1); HIV-1 infection (1); Immunodeficiency (1); inflammatory myopathies (1); Lipoatrophy (1); malaria (1); oral cancer (1); rectal cancer (1); scleromyositis (1).